CRP (C-reactive protein)
Diseases named in the same sentence as CRP in open-access papers (continued):
Sharing a sentence is not in itself a finding about the gene and the disease.
apical periodontitis (9 papers, 2021 to 2025). "Apical periodontitis is associated with elevated levels of inflammatory markers such as interleukins, immunoglobulins, and C-reactive protein in humans." (PMID 40094984, 2025). "This prospective observational cohort study aimed to evaluate the impact of endodontic treatment or retreatment on serum CRP levels in patients with symptomatic and asymptomatic apical periodontitis and assess demographic influences." (PMID 41464835, 2025). "This study aimed to evaluate the short-term impact of endodontic treatment or retreatment on serum CRP levels in patients with symptomatic and asymptomatic apical periodontitis and to assess demographic influences." (PMID 41464835, 2025). "They found that apical periodontitis correlates with poorly controlled diabetes and elevated CRP levels." (PMID 41464835, 2025). "Apical periodontitis has previously been shown to elevate serum CRP levels by inducing low-grade systemic inflammation." (PMID 39797322, 2025). "Enhanced CRP synthesis, in response to IL-6 in apical periodontitis, can act as a potential reservoir of IL-6 and CRP for sustaining a low systemic inflammatory response, thus increasing the risk for atherosclerotic cardiovascular disease." (PMID 35888650, 2022). "A previous histological study reported increased IL-6 and CRP messenger RNA levels in periodontal ligament tissue of teeth with apical periodontitis." (PMID 35888650, 2022). "Some limitations of this study included its short follow-up study design, which prevented the establishment of a causal relationship between apical periodontitis and CRP levels, as well as the lack of operator blinding, single-population focus, and assessment of only CRP." (PMID 41464835, 2025). "According to a systematic review and meta-analysis we conducted recently, systemically healthy individuals with apical periodontitis presented higher C reactive protein (CRP) values than healthy individuals without AP." (PMID 33490705, 2021). "However, the specific impact of root canal retreatment on levels of CRP in patients with apical periodontitis has not been fully explored." (PMID 41464835, 2025). "This study's objective was to determine the impact of apical periodontitis (AP) and non-surgical root canal treatment (NSRCT) on the levels of serum high-sensitivity C-reactive protein (hs-CRP) and cardiovascular risk in patients with cardiovascular disease (CVD)." (PMID 40792328, 2025).
atrial flutter (9 papers, 2014 to 2025). A disorder characterized by an electrocardiographic finding of an organized, regular atrial rhythm with atrial rate of 240-340 beats per minute. "Elevated inflammatory markers, particularly C-reactive protein (CRP), have been associated with an increased risk of AF and atrial flutter, highlighting inflammation as a key driver of arrhythmogenicity." (PMID 40151738, 2025). "Elevated CRP levels and electrolyte disturbances can be associated with atrial arrhythmogenesis, but direct clinical evidence proving that proactive correction prevents new-onset atrial flutter remains limited." (PMID 40151738, 2025). "In addition, a prospective study on patients with atrial flutter also found that after radical ablation, the levels of CRP (6.28 mg/L vs. 2.92 mg/L, p = 0.028) and IL-6 (p = 0.002) in patients with atrial flutter significantly decreased." (PMID 40709209, 2025). "In addition, previous studies showed that C-reactive protein and IL-6 serum levels were significantly decreased in patients with atrial flutter after successful ablation." (PMID 38988665, 2024).
bronchopulmonary dysplasia (9 papers, 2017 to 2026). Bronchopulmonary dysplasia is a chronic respiratory disease that results from complications related to lung injury during the treatment of infant acute respiratory distress syndrome in low-birth-weight premature infants or from abnormal lung development in older infants. "In contrast, clinical symptoms of funisitis appear to represent relatively more foetal conditions, such as leucocytosis, elevated CRP and immunoglobulin M at birth, bronchopulmonary dysplasia, and cerebral palsy." (PMID 34408219, 2021).
candidiasis (9 papers, 2016 to 2026). Infection with the organism Candida. "In clinical settings, patients with clinical suspicion of invasive candidiasis that present with high CRP and low PCT levels should undergo prompt blood culture sampling combined with simultaneous non-culture biomarker assessment." (PMID 41590467, 2026). "PCT and CRP are well-known for their predictive value in assessing the prognosis of patients with candidiasis and bacterial infections." (PMID 39250466, 2024). "The potential for diagnosing candidiasis using three early inflammatory biomarkers of C-reactive protein (CRP), procalcitonin (PCT), and presepsin (PSEP) were also evaluated." (PMID 35330311, 2022). "The IL-6 and CRP values are the most increased in a candida infection." (PMID 40242671, 2025). "In addition, patients with candidiasis (CRP: 12.5 mg/l) had significantly higher mean levels of C-reactive protein (CRP: 12.5 mg/l) than patients without candidiasis (CRP: 6.8 mg/l, p < 0.001)." (PMID 40322330, 2025).
chronic fatigue syndrome (9 papers, 2012 to 2024). "Previous investigation into CRP demonstrated it to be significantly elevated in those with post-treatment Lyme disease, compared to those with myalgic encephalomyelitis/chronic fatigue syndrome." (PMID 38399784, 2024). "At the point of screening, those who participated in this study showed a relatively high degree of fatigue, but the value of high-sensitivity CRP before intervention was found to be lower than in other reports that employed patients who faced cancer-related fatigue and had chronic fatigue syndrome." (PMID 35684157, 2022). "It has been reported that CRP can reflect the severity of EBV infection, chronic fatigue and chronic fatigue syndrome are triggers of acute EBV infection." (PMID 34525962, 2021).
chronic hepatitis C (9 papers, 2013 to 2025). "Design: Anthropometric, hemodynamic, dietary, and biochemical parameters, CRP and liver enzymes were measured in 43 adult patients of both genders who were diagnosed with chronic hepatitis C and were under antiviral therapy." (PMID 28469541, 2017). "Patients with chronic hepatitis C also exhibit high serum levels of C reactive protein (CRP), which is a marker of inflammation." (PMID 28469541, 2017). "Levels of inflammatory markers like IL-6, TNF-α and CRP are elevated in patients with chronic hepatitis C." (PMID 25438910, 2014). "A correlation has been suggested between increased CRP levels and lipid metabolism disorders in patients with chronic hepatitis C. Several studies have shown that HCV follows the lipoprotein pathway inside the hepatocytes to survive in the host and increase its viral load." (PMID 28469541, 2017).
colorectal adenoma (9 papers, 2012 to 2021). An adenoma that arises from the colon or rectum. "The observed positive association of plasma CRP level with colorectal adenoma overall as well as in male subjects, however, lost statistical significance when further adjusted for BMI." (PMID 28667300, 2017). "Of importance, the present study showed a clear influence of BMI on the association between plasma concentrations of CRP and colorectal adenoma." (PMID 28667300, 2017). "We quantified plasma concentrations of CRP using a highly sensitive method which enables the assessment of even low-grade inflammation, and evaluated the association between CRP level and the prevalence of colorectal adenoma." (PMID 28667300, 2017). "In summary, this study in a middle-aged and elderly Japanese population showed a positive association between plasma CRP level and colorectal adenoma, notably in larger and multiple adenomas." (PMID 28667300, 2017). "In this study, we observed a positive association between plasma CRP concentration and the prevalence of colorectal adenoma." (PMID 28667300, 2017). "Circulating CRP levels were associated with an increased risk of multiple small tubular or advanced colorectal adenomas, and the association was more pronounced among current smokers and never/former nonsteroidal anti-inflammatory drugs users." (PMID 27608842, 2016). "Nonetheless, epidemiological studies evaluating the association between circulating CRP level and colorectal adenoma have been inconclusive, with 3 of the 10 studies showing a positive association versus null results or even an inverse association in the others." (PMID 28667300, 2017). "The pooled results on CRP and IL-6 and risk of colorectal adenomas are consistent with those from nested case-control studies in which circulating levels measurement preceded colorectal adenomas incidence." (PMID 27608842, 2016). "Serum TIMP-1 is useful in differentiating between CRC and colorectal adenomas, whereas M-CSF and CRP are independent prognostic factors for the survival of patients with CRC." (PMID 34071492, 2021). "Some RCTs have indicated significant favorable effects of vitamin D supplementation on inflammatory cytokines such as IL-6, sTNF-R2, and CRP, but only in precisely chosen groups of diabetics patient and patients with colorectal adenoma." (PMID 31350967, 2019). "Evidence for this possible gender difference in colorectal adenoma in relation to circulating CRP remains limited, and further investigation is warranted." (PMID 28667300, 2017). "The OR of colorectal adenoma for the highest compared to the lowest quartile of plasma CRP in the overall population was 1.30 (95% CI 0.94–1.79), with P trend = 0.031." (PMID 28667300, 2017). "The evidence linking CRP concentrations with colorectal adenoma development, a precursor in the natural history of colorectal neoplasia, is weaker." (PMID 26321888, 2015). "Plasma CRP concentrations was positively associated with the prevalence of colorectal adenoma, albeit in a nonlinear manner." (PMID 28667300, 2017). "A meta-analysis confirmed the association between circulating levels of C-reactive protein (CRP), a non-specific marker of systemic inflammation, and risk of colorectal adenoma." (PMID 33182693, 2020). "Results from publications on inflammatory markers of C-reactive protein (CRP), interleukin-6 (IL-6) and tumor necrosis factor-α (TNF-α) and risk of colorectal adenomas are not consistent." (PMID 27608842, 2016). "The departure from a linear relationship was not significant between CRP (Pfor nonlinearity=0.18), IL-6 (Pfor nonlinearity=0.35) and TNF-α (Pfor nonlinearity=0.87) and risk of colorectal adenoma, respectively." (PMID 27608842, 2016). "For highest vs. lowest levels, results from this meta-analysis did not support an association between circulating levels of CRP [OR (95% CI): 1.15 (0.94-1.40)], IL-6 [1.17 (0.94-1.46)] and TNF-α [0.99 (0.75-1.31)] and risk of colorectal adenomas, respectively." (PMID 27608842, 2016).
colorectal adenoma (continued). "Colorectal adenoma cases in our study were not pathologically verified, and single measurement of plasma CRP may not have completely represented random variation within the subjects." (PMID 28667300, 2017). "Circulation levels of CRP, IL-6 and TNF-α might be not useful biomarkers for identifying colorectal adenomas, respectively." (PMID 27608842, 2016). "In summary, circulating levels of CRP, IL-6 and TNF-α may be not useful biomarkers for identifying colorectal adenomas." (PMID 27608842, 2016).
congenital heart disease (9 papers, 2016 to 2025). A heart disease that is present at birth. "However, there are doubts regarding how high-sensitivity C-reactive protein (hs-CRP) impacts patients with congenital heart disease (CHD)." (PMID 38673472, 2024). "CRP, BNP, and cTnI were risk factors of congenital heart disease (p < 0.05); cTnI, hs-CRP, BNP, and Lp(a) were significantly close to congenital heart disease (p < 0.01)." (PMID 27118988, 2016).
Cough (9 papers, 2007 to 2025). A sudden, audible expulsion of air from the lungs through a partially closed glottis, preceded by inhalation. "In the multivariate model, four characteristics were independently associated with the diagnosis: male gender, acute cough, C-reactive protein, and urea." (PMID 30991716, 2019). "In an earlier study of patients with acute cough, it was shown that CRP influenced a GP’s decision on whether to prescribe antibiotics or not, but physicians with an already restrictive antibiotic prescription rate were not affected." (PMID 33399009, 2020).
dental caries (9 papers, 2016 to 2025). The decay of a tooth, in which it becomes softened, discolored, and/or porous. "Mediation analysis indicated that four inflammatory indicators (CRP, leukocyte, neutrophil, lymphocyte) mediated the association between vitamin B12 and dental caries." (PMID 41384444, 2025). "CRP, leukocyte, neutrophil and lymphocyte were significantly mediated the association between vitamin B12 and dental caries risk (proportion mediated (PM), 0.91%, P = 0.038; PM, 0.958%, P = 0.046; PM, 1.16%, P = 0.008; PM, 1.02%, P = 0.024)." (PMID 41384444, 2025). "Parket al.17 noted the high CRP/albumin ratio in cases of dental caries and its association with disease for long periods, and thus decreased survival rates." (PMID 37224312, 2023). "During pregnancy, dental caries, hookworm and vaginal diplococcal infection were associated with higher CRP or increased the odds of trimester-specific elevated CRP whereas Ascaris, Lactobacillus and Bacteroides/Gardnerella were negatively associated with an elevated CRP." (PMID 28571565, 2017). "Comparison between smokers with dental caries and healthy group, according to BMI, age, sex, CRP, and CPITN." (PMID 37224312, 2023). "Correlation between salivary IgA, IL-1β, CRP, BMI, age, and sex insmokers with dental caries." (PMID 37224312, 2023).
dilatation (9 papers, 2012 to 2026). "Preoperative cervical dilatation ≥ 3.0 cm, prolapsed membranes into the vagina, preoperative CRP ≥ 11.1, and NLR ≥ 7.1 were associated with increased odds of PTB before GA 28 weeks." (PMID 38248739, 2023). "The sustained increase in plasma CRP concentration in the course of MI observed in the group of patients with LV dilatation may have been associated with a greater extent of myocardial damage reflected by the values of cardiac necrosis markers." (PMID 22973074, 2012). "Variables assessed included the serum procalcitonin level, abnormal ultrasound findings (ureteral dilatation, pelvicalyceal dilatation, and renal length), age, sex, family history of uropathy, and serum C-reactive protein level at hospitalisation." (PMID 41517569, 2026). "The procalcitonin and CRP levels, pelvicalyceal dilatation, and ureteral dilatation were all statistically significant for high-grade VURs on univariate analysis." (PMID 41517569, 2026). "Previous studies have identified a few risk factors for coronary dilatation or aneurysmal formation, including late IVIG treatment, IVIG unresponsiveness, and several clinical biomarkers, such as serum albumin levels and CRP levels." (PMID 28587647, 2017). "The following variables were entered into the forward selection logistic regression model as predictors associated with SPTD at <32 weeks: VDBP, TIMP-1, and DKK3 in the CVF, serum CRP, cervical dilatation, vaginal progesterone therapy, and use of corticosteroids." (PMID 28700733, 2017). "In addition, C-reactive protein may increase reactive oxygen species and enhance LA fibrosis, leading to atrial dilation and atrial dysfunction." (PMID 34674646, 2021). "This study demonstrated that the degree of cervical dilatation at diagnosis; WBC count, ANC, and CRP levels in the maternal peripheral blood; and IL-6 concentration in the amniotic fluid significantly differed between the successful and failure groups (all P < .05)." (PMID 38552048, 2024). "Using the ROC curve analysis, we evaluated the predictive power of the serum CRP levels, WBC count, ANC, PLR, and degree of cervical dilatation in maintaining pregnancy for >4 weeks after rescue cerclage compared to the IL-6 concentration in the amniotic fluid." (PMID 38552048, 2024).
erysipelas (9 papers, 2012 to 2025). An infection of the upper layers of the skin caused by species of streptococcus. "High CRP levels and leukocyte counts (i.e., a more severe inflammatory response) in erysipelas are associated with recurrence of erysipelas." (PMID 23437094, 2013). "However, traditional biomarkers like C-reactive protein (CRP) and white blood cell counts lack specificity for erysipelas, whereas elevated procalcitonin (PCT) levels have shown a high discriminatory value, correlating with infection severity and aiding in the differentiation from DVT." (PMID 40400624, 2025). "No specific tests or imaging is needed to diagnose erysipelas; however, a few lab parameters like white blood cell counts, sedimentation rate, and CRP may be helpful in predicting prognosis or evolving complications." (PMID 39027802, 2024). "Furthermore, patients with BHS in the perianal area tended to have more pronounced signs of inflammation with higher CRP and lower systolic blood pressure than patients with erysipelas without BHS isolation." (PMID 31292789, 2019). "This is because only one previous study showed differences in CRP and WBC between patients with erysipelas and those with recurrent erysipelas, but other studies showed no such differences." (PMID 33413190, 2021).
falciparum malaria (9 papers, 2010 to 2024). "In the presence of falciparum malaria, CRP levels increased in both study groups, corroborating several previous reports." (PMID 27298824, 2016). "Children with severe vivax malaria had higher median hemoglobin concentrations, smaller spleens, higher median plasma sodium concentrations, and lower median plasma bilirubin and CRP concentrations than children with severe falciparum malaria." (PMID 22216212, 2011). "The model could explain about 59% of the observed variation in CRP levels of respondents who had falciparum malaria." (PMID 27298824, 2016). "The higher plasma CRP concentrations in vivax malaria might be explained by a heightened inflammatory host response as compared with falciparum malaria." (PMID 27386859, 2016). "CRP elevation has been proposed as an excellent measure of parasitemia in falciparum malaria." (PMID 24167754, 2013). "Together these epidemiological and genetic associations suggest that, in addition to its utility as a prognostic marker in falciparum malaria, CRP may play a deleterious role in the disease." (PMID 24167754, 2013). "Conventional inflammation markers such as C-reactive protein (CRP) and procalcitonin (PCT) can be elevated in patients with bacterial infections, but also in falciparum malaria, rendering their discrimination a clinical challenge." (PMID 37889376, 2024). "Empiric antibiotic therapy in returning travellers with falciparum malaria should not be guided by CRP levels or radiographs of the thorax alone." (PMID 37889376, 2024). "Considering the fact that individuals with asymptomatic Plasmodium falciparum infection exhibit low circulating CRP levels, the elevated level of CRP in falciparum malaria patients in the current study should not be seen as an ordinary acute phase response." (PMID 27298824, 2016). "Therefore, the current study seeks to examine changes in levels of CRP, lipid peroxides, and total antioxidant power (TAP) due to falciparum malaria in the same individual with T2DM compared with age-matched nondiabetic controls, over a two-year period, in the Cape Coast metropolis of Ghana." (PMID 27298824, 2016).
Genital ulcers (9 papers, 2008 to 2026). "The association of CRP with genital ulcer (P = .001), ocular lesion (P = .001),vascular lesion (P = .001), EN/PPE (P = .043), and the presence ofpositive pathergy test (P = .016) was found." (PMID 19197380, 2008).